MMP1 (matrix metallopeptidase 1)
Diseases named in the same sentence as MMP1 in open-access papers (continued):
Sharing a sentence is not in itself a finding about the gene and the disease.
gastric cancer (continued). "MMP-1 plays a pivotal role in cancer progression and poor prognosis in colon-rectal, oesophageal and gastric cancer has been correlated with high MMP-1 expression." (PMID 15740610, 2005). "The MMP-1 expression was higher in the intestinal-type gastric cancer than in the diffuse one." (PMID 35163805, 2022). "Specifically, the extensive role of MMP1 in metastasis of gastric cancer has been reported." (PMID 33921173, 2021). "In recent years, it has been shown that MMP-1 protein is an unfavorable prognostic marker for a number of cancers, including salivary gland cancer, nasopharyngeal carcinoma, gastric cancer, thyroid follicular carcinomas, esophageal squamous cell carcinoma, and OSCC." (PMID 32823758, 2020). "This suggests MMP-1 functional polymorphic haplotypes may be a prognostic factor for locoregional gastric cancer progression." (PMID 24505369, 2014). "Moreover, miR-145 regulates the expression of Ets1 and its downstream genes, matrix metalloproteinase-1 (MMP-1) and-9, thus inhibiting the invasion, metastasis and angiogenesis of gastric cancer cells." (PMID 25124875, 2014). "MMP-1.1 and MMP-1.2 polymorphisms did not confer any significant risk for tumor location or degree of tumor progression in gastric cancer." (PMID 24505369, 2014). "However, we have found a functional correlation of MMP-1 promoter polymorphic haplotypes with MMP-1 expression in a locoregional manner of gastric cancer occurrence." (PMID 24505369, 2014). "H. pylori infection may be involved in gastric cancer metastasis through the mechanism of upregulating the expression of MMP-1 and MMP-10." (PMID 25120597, 2014). "The extended haplotype frequency distributions of MMP-1 polymorphisms were not significant between gastric cancer patients and controls and none of these haplotypes conferred risk for gastric cancer occurrence (data not shown)." (PMID 24505369, 2014). "Furthermore, compared with levels in the gastric cancer specimens, the expression levels of MMP-1 and MMP-10 in the metastatic gastric cancer specimens were significantly higher (P<0.05)." (PMID 25120597, 2014). "Although the enhanced expression of MMP-1 was associated with local invasion and poor prognosis in gastric cancer, the role of the MMP-1 promoter SNPs and their haplotypes in the development of gastric cancer is currently unknown in any human population." (PMID 24505369, 2014). "H. pylori infection may promote the invasion and metastasis of gastric cancer by increasing the expression of MMP-1 and MMP-10." (PMID 25120597, 2014). "Furthermore, in gastric cancer models HER-2 has been shown to increase the transcription of MMP-1 through the activation of the MMP-1 promoter, and HER-2 knockdown resulted in its downregulation." (PMID 23766685, 2013). "Loss of HIF-1α may contribute to the development of aggressive peritoneal dissemination via the upregulation of MMP-1 in gastric cancer cells." (PMID 23181099, 2012). "Taken together, our results and the previous findings indicate that the upregulation of MMP-1 expression following the loss of HIF-1α might be an important step in the development of peritoneal dissemination from MKN45 and MKN74 gastric cancer cells." (PMID 23181099, 2012). "Moreover, in gastric cancer, most of the studies on MMP-1 have only focused on the importance of the SNP (−1607 1G/2G) in the promotor in relatively small samples." (PMID 22655095, 2012). "Furthermore, a SNP in the MMP-1 promoter was demonstrated to be correlated with histological differentiation of gastric cancer." (PMID 22655095, 2012). "Thus, a large sample and more polymorphic sites are critical to understanding the role of MMP-1 SNPs in gastric cancer development." (PMID 22655095, 2012). "Hence, a large sample and more polymorphic sites are critical for understanding the role of MMP-1 SNPs in gastric cancer development." (PMID 22655095, 2012).
gastric cancer (continued). "Through the DNA microarray studies after galectin-3 silencing, we demonstrated here that galectin-3 plays a key role in up-regulating the expressions of protease-activated receptor-1(PAR-1) and matrix metalloproteinase-1(MMP-1) PAR-1 thereby promoting gastric cancer metastasis." (PMID 21966428, 2011). "hese findings led us to hypothesize that galectin-3, PAR-1 and MMP-1 may be involved in enhancing the migration and invasion of gastric cancer." (PMID 21966428, 2011). "Also several studies found that MMP-1 plays a crucial role in metastasis of breast cancer, liver and colon cancers, and gastric cancers, among others." (PMID 21966428, 2011). "Additionally, in the in vitro experiment, it was evidenced that TAMs may stimulate the expression of MMPs (MMP1, 3 and 10) and migration of gastric cancer cells." (PMID 34203461, 2021). "So, the presence of polymorphic alleles of the MMP-1 promoter may not necessarily contribute to the degree of tumor invasion and in addition to progression of gastric carcinoma." (PMID 24505369, 2014). "AQP3 serves a key role in the progression and metastasis of various types of cancer: AQP3 can upregulate matrix metalloproteinases (MMP1, MMP2 and MMP9) and induce EMT by activating the PI3K/AKT signaling in gastric cancer." (PMID 39611488, 2025). "MMP-1 and MMP-13 are both often overexpressed in epithelial cancers such as breast, prostate, and gastric cancer." (PMID 37055381, 2023). "Even more, in gastric cancer cell lines, AQP3 overexpression upregulated matrix metalloproteinases MT MMP1, MMP2, and MMP9, while its silencing decreased them via a PI3K/Akt-dependent manner." (PMID 37175840, 2023). "H. pylori infection increases the expression and secretion of various MMPs, including MMP-1, MMP-9, MMP-7, and MMP-10, in the gastric epithelial cells or gastric cancer cells." (PMID 33809289, 2021). "Recent studies have found that TAMs highly express certain cytokines in gastric cancer, such as VEGF-A, VEGF-C, matrix metalloproteinase 1 (MMP-1) and amphiregulin, and induces capillary morphogenesis in human gastric cancer lymphatic ECs." (PMID 34988011, 2021). "The constructed network pharmacology revealed the significant interaction among the predicted targets that led to the identification of three core proteins (CDK2, MMP1, and HSP90) as the active bio targets of PG in gastric cancer." (PMID 33921173, 2021). "In liver and gastric cancer types, ETV4 positively modulates MMP1 by binding the MMP1 promoter regions." (PMID 32982961, 2020). "In a gastric cancer study, HER2 knockdown led to downregulation of the expression of MMP-1, while HER2 overexpression enhanced the transcription of MMP-1 through the activation of a specific promoter." (PMID 31443252, 2019). "A study in gastric cancers revealed that CREPT increases cell migration by regulating E-cadherin, vimentin, N-cadherin, and matrix metalloproteinase 1 (MMP-1) expressions." (PMID 31877646, 2019). "In gastric cancer, inhibiting HOTAIR reverses the EMT process and reduces invasiveness mediated by MMP1 and MMP335." (PMID 28931862, 2017). "Among the hits identified in the CagA screen, 4 of them (MMP1, CEACAM6, ITGA2, C3) showed at least 2-fold increases in gastric cancer when compared to normal controls." (PMID 27421133, 2016). "Statistically, the expression levels of MMP-1 and MMP-10 were significantly higher in the gastric cancer specimens than those in the chronic gastritis specimens (P<0.05)." (PMID 25120597, 2014). "The genotype frequency distribution, (AA vs. TT, TA and TA+TT) of the MMP-1.3 polymorphism in the patient population was not significantly different from healthy controls (p = 0.626, p = 0.999 and p = 0.806 respectively) and thus did not confer any significant risk for gastric cancer." (PMID 24505369, 2014). "MMP-1 and MMP-10 expression in patients with gastric cancer and in those with metastatic gastric cancer was significantly higher than that in patients with gastritis." (PMID 25120597, 2014).
gastric cancer (continued). "The positive expression of MMP-1 and MMP-10 was associated with lymph node metastasis and clinical stage, but not with age, gender or differentiation degree, indicating that MMP-1 and MMP-10 expression was involved in gastric cancer metastasis." (PMID 25120597, 2014). "H. pylori infection and MMP-1 and MMP-10 expression were detected in gastric cancer and chronic gastritis specimens." (PMID 25120597, 2014). "However, a study on a Japanese population (215 patients) showed that, although the presence of the 2G allele (−1607) in the MMP-1 promoter did not enhance the risk of gastric cancer, it may be involved in differentiation of gastric cancer." (PMID 22655095, 2012). "In conclusion, our studies demonstrated that galectin-3 accelerated gastric cancer cell motility by up-regulating of PAR-1 and MMP-1." (PMID 21966428, 2011). "A lentivirus (pLECE3 Vector) containing MMP-1 expression cassette regulated by CMV promoter was prepared and infected in AGS gastric cancer cells." (PMID 21966428, 2011). "We confirmed that up-regulation of MMP-1 by galectin-3 is important for the activation of PAR-1 signaling and increased gastric cancer cells invasion." (PMID 21966428, 2011). "Once H.Pylori has infected the stomach, it can stimulate the secretion of MMP-1, MMP-2, MMP-3 and TIMP-3 from gastric cancer cell, and finally prompt and speed up the progress invasion and metastasis of gastric cancer." (PMID 20637122, 2010). "The key targets of Zuojin pill MMP1, MMP3, and MMP9 play a therapeutic role in gastric cancer." (PMID 39086391, 2024). "In about 73% of the cases of advanced cancer, MMP-1 immunoreactivity was associated significantly with peritoneal metastasis and lymph-node metastasis, as well as with worse survival in comparison to MMP-1-negative gastric cancer." (PMID 35163805, 2022). "Moreover, a decreased expression of both MMP-1 and MMP-2 in gastric cancer tumors in patients treated with cisplatin and supplemented with PUFAs was also observed." (PMID 34203461, 2021). "As signaling pathways for MMP expression, H. pylori infection induces MMP-1 expression via c-Jun N-terminal kinase (JNK) and extracellular-signal-regulated kinase (ERK) pathways in gastric cancer cells and MMP-10 expression via the ERK pathway in gastric epithelial cells." (PMID 33809289, 2021). "However, positive staining for MMP-1 and MMP-10 was detected in the poorly and moderately differentiated gastric cancer and gastric cancer with lymph node metastasis specimens." (PMID 25120597, 2014). "In this study, the results indicate that in the H. pylori-induced MMP secretion in gastric cancer cells, MMP-10 may be involved in the activation of MMP-1." (PMID 25120597, 2014). "It was also found that MMP-1 expression was correlated with MMP-10 expression, indicating that these two different types of MMPs may play a synergic role in gastric cancer genesis, invasion and metastasis." (PMID 25120597, 2014). "MMP-1.1, MMP-1.2, MMP-1.3, MMP-1.4 and MMP-1.5 polymorphisms did not play any role in determining gastric cancer risk for any age group, gender or tobacco-addiction status." (PMID 24505369, 2014). "Finally, great of relevance, we found an upregulation of Matrix Metalloproteinase family (MMP1, MMP3, MMP10, MMP12), that are overexpressed in gastric cancer as a result of NF-Kb activation thus promoting migration and invasion, and are associated with poor prognosis." (PMID 34012923, 2021). "Several molecular targets were previously used to detect CTCs/DTCs in patients with gastric cancer, including CEA, mucin 1, c-Met, human telomerase reverse transcriptase (hTERT), epithelial cell adhesion molecule (EpCAM), survivin, and matrix metalloproteinase-1 (MMP-1)." (PMID 30056567, 2019).
gastric cancer (continued). "Despite this, in our study MMP-1.1 polymorphism and additionally four other SNPs (MMP-1.1, MMP-1.2, MMP-1.3 and MMP-1.4) in the promoter region are not correlated with gastric cancer occurrence, suggesting these promoter variants to be low penetrance risk factors in gastric cancer." (PMID 24505369, 2014). "Thus, the simultaneous detection of MMP-1 and MMP-10 may be important in the evaluation of the prognosis and metastasis of gastric cancer." (PMID 25120597, 2014). "This study showed that RFP labeled gastric cancer cells invaded blood vessels while galectin-3, MMP-1 or PAR-1 silenced gastric cancer cells could not." (PMID 21966428, 2011). "Therefore, an increase in MMP-1 expression promoted by galectin-3 might have dual effects, namely, PAR-1 activation and ECM degradation, and both are critical for gastric cancer metastasis." (PMID 21966428, 2011). "This study has shown that MMP-1 and MMP-10 expression was higher in patients with gastric cancer with metastasis than in those with gastric cancer without metastasis." (PMID 25120597, 2014). "It was revealed that MMP-1 and MMP-10 expression was significantly positively correlated in gastric cancer (r=0.8321, P<0.05; data not shown)." (PMID 25120597, 2014).
colon carcinoma (54 papers, 2010 to 2026). "Studies have shown that high expression of MMP-1 is associated with local and distant metastasis in colon cancer." (PMID 35479956, 2022). "Studies have shown that MMP1 is associated with lung squamous cell carcinoma, colon cancer and adenocarcinoma." (PMID 34721544, 2021). "MMP1, a matrix metalloproteinase associated with more aggressive tumors and whose expression is induced by M3R activation in human colon cancer cells, was almost uniformly over-expressed in adenocarcinomas compared to normal colon." (PMID 28416748, 2017). "The level of MMP1 expression is closely related to the prognosis of patients with colon cancer, and the mechanism of MMP1 may be associated with its involvement in the metastasis and spread of tumors." (PMID 36147444, 2022). "Indeed, the levels of expression and activation of M3 muscarinic receptors in colon cancer cells are very high and associated with increased tumor cell proliferation by activation of the MAPKinase pathways and invasiveness by increasing MMP1 release." (PMID 30657060, 2019). "Distinct colon cancer-associated fibroblast (CAF) subtypes were found to express different MMP combinations, including MMP1/3-expressing and MMP11-expressing CAFs." (PMID 42079046, 2026). "Increased MMP-1 expression levels have been correlated with high mortality rates in several malignancies, including breast, lung, gastric, and colon carcinomas." (PMID 40564842, 2025). "Our results are in accordance with previous studies indicating that a higher level of circulating MMP-1 is related to prognosis in patients with colon cancer." (PMID 38954024, 2024). "This study reports that galectin-3 secretion by human colon cancer cells induces cancer cell secretion, in an autocrine/paracrine manner, of a number of proteases including cathepsin-B, MMP-1 and MMP-13." (PMID 37055381, 2023). "Treatment of colon cancer cells with miR-34a reduced MMP-1 and -9 protein levels and decreased proliferation and invasion in vitro." (PMID 38288108, 2023). "Subsequent work indicated that blocking muscarinic receptor activation or the activity of MMP-1, whose expression correlates with advanced colon cancer stage, tumor metastasis, and reduced survival, abolished acetylcholine-induced colon cancer cell invasion." (PMID 38288108, 2023). "In this study, we explored the cancer inhibitory effect of kaempferol by evaluating the biological behavior of two human colon cancer cells intervened by this drug and investigating changes in the expression of MMP1, 2, and 9 genes." (PMID 36147444, 2022). "In the current study, we also observed that Amaryllidaceae alkaloids provoked a strong decrease in MMP-1, -2, and -7 secretion by cultured colon cancer cells." (PMID 36139106, 2022). "A DAVID analysis was performed by selecting genes positively correlated with the expression patterns of SERPINE1 and MMP1 from the TCGA colon cancer cohort." (PMID 36076991, 2022). "Altogether, these data indicated that exogenous MMP1 secreted by TAMs contributed to the proliferation of colon cancer cells by accelerating the cell cycle transition from G0/G1 to S and G2/M phase." (PMID 34753916, 2021). "Based on these observations, we concluded that MMP1/PAR1 axis facilitates colon cancer cell proliferation through MAPK/Erk pathway." (PMID 34753916, 2021). "To further evaluate the role of MMP1/PAR1/Erk1/2 axis in the tumor formation ability of colon cancer cells in vivo, we injected TAMs+HT-29 cells into BALB/c mice to establish a model of subcutaneous xenografts." (PMID 34753916, 2021). "In vitro, darifenacin also appeared to suppress ACh-stimulated colon cancer cell invasion, with a corresponding suppression of MMP1 mRNA expression, presumably via inhibition of p38, ERK1/2, and Akt signaling." (PMID 34884958, 2021).